ITGA11 (integrin subunit alpha 11)
Diseases named in the same sentence as ITGA11 in open-access papers (continued):
Sharing a sentence is not in itself a finding about the gene and the disease.
tumor (continued). "We constructed ITGA11 knockdown tumor models in MKN45 and AGS to clarify the influence of ITGA11 on tumor growth and metastasis in vivo." (PMID 34802381, 2021). "Results showed that ITGAV (10/10), ITGA2 (7/10), ITGA3 (8/9), ITGA4 (7/10), ITGA6 (7/8), and ITGA11 (7/9) protein levels were increased in tumour tissues compared with adjacent tissues." (PMID 34709754, 2021). "Further, we used IGF-1 to activate the PI3K/AKT pathway and discovered that IGF-1 elevated tumor growth and weakened the tumor-suppressive effect mediated by ITGA11 knockdown in GC." (PMID 34802381, 2021). "Alternatively, tumor cell lysates from ITGA11−/− mice reduce the levels of activated ERK1/2 compared with those from ITGA11+/+ mice." (PMID 33682233, 2021). "More importantly, patients with high ITGA11 expression had larger tumor volume, later clinical staging, and more distant metastasis and vascular invasion (vs. patients with lower ITGA11 expression)." (PMID 34802381, 2021). "Representative tumor sections showed higher ITGA11 and COL11A1 expressions in intratumoral cancer epithelium and cancer stroma compared to normal lung tissue." (PMID 33682233, 2021). "Moreover, in carcinoma-associated fibroblasts (CAFs), ITGA11 signaling pathway may play an important role in carcinoma-associated fibroblasts (CAFs), which means Integrin α11β1 can promote tumor growth and metastatic potential of NSCLC cells by regulating cancer stromal stiffness." (PMID 31875161, 2019). "Reconstitution of N-MSCs with four genes, GREM1, LOXL2, ADAMTS12 and ITGA11 that contributed to the T-MSC phenotype increased their ability to promote primary tumor cell dissemination." (PMID 29503225, 2018). "Expression of ITGA11 mRNA exhibited a significant (p < 0.0001) 3.88-fold increase in tumor tissues." (PMID 41373732, 2025). "Pharmacological inhibition of PDGFRB impaired tumor cell invasion induced by ITGA11-positive CAFs." (PMID 39335478, 2024). "However, the antitumor effects of siRNA in a mouse xenograft tumor model demonstrated that ITGA11 siRNA treatment outperformed EZH2 siRNA treatment, indicating the superior efficacy of ITGA11 siRNA in suppressing tumor growth." (PMID 38664825, 2024). "In BC, ITGA11/PDGFRB + CAFs displayed tumor-promoting features, though their expressions in BC may be relatively small and weak association with strSPARC." (PMID 39335478, 2024). "Fibrogenesis in S‐ECM samples is likely due to the presence of an activated cancer‐associated fibroblast (CAF) population in the tumor microenvironment, as indicated by the identification of CAF marker genes as key regulators for S‐ECM, including FAP, ACTA2, PDGFRB, VCAN, and ITGA11." (PMID 36637997, 2023). "Inspection of picrosirius red-stained tumor samples under polarized light showed that collagen fibers in Itga11−/− tumors often appeared orange or red, whereas they were yellow or green in Itga11+/+ control tumors, indicating the presence of thicker collagen fibers in the knockout samples." (PMID 36003785, 2022). "Moreover, we described a correlation with a CAF phenotype for CAFs expressing high levels of ITGA11 and a tumor-promoting role of ITGA11 when expressed in CAFs; integrin α11 is a collagen I receptor, and it has been involved in cell motility." (PMID 34769388, 2021). "As a result, ITGA11 was highly expressed in GC tissues versus non-tumor tissues (P < 0.05)." (PMID 34802381, 2021). "Furthermore, we investigated the correlation between tumor stage and the expression levels of ITGA11, ITGB4 and ITGB8." (PMID 31875161, 2019). "High ITGA11 expression in the tumor stroma is a marker of poor prognosis in NSCLC patients." (PMID 29503225, 2018). "Notably, YAP-1 signalling preserved expression of both integrin beta-1 and ITGA11 implying auto-regulation similarly to YAP-1’s function in cancer-associated fibroblasts, where MYL9 was a key regulator of the ECM and tumour invasion." (PMID 27535340, 2016).
tumor (continued). "However, we did not observe any association between ITGA11/ Jab1 and histological type, tumor stage, family history nor menopause." (PMID 29383106, 2017). "Integrin α11 (ITGA11), a integrin family members, involve in various processes that influences the cell’s biological behavior, such as metastasis, embryogenesis, hemostasis, immune response, tissue repair, cancer growth, tumor angiogenesis, and resistance to therapy." (PMID 29383106, 2017). "These patients whose Gleason score was higher than 7 or who were in tumor stages III and IV showed strong positive staining of ITGA11 (Gleason score, P = 0.049, pathological tumor stage, P = 0.022)." (PMID 35293897, 2022). "For the aim of confirming PI3K pathway activation can reversed the anti-tumor role-mediated by si-ITGA11, we added the ITGA11 knockdown plasmid and/or PI3K/AKT agonist IGF-1 into MKN45 to explore the specific mechanism of ITGA11 in GC progression." (PMID 34802381, 2021). "Expression of ITGA11 was negatively correlated with CDH1, whereas positively correlated with VIM or CDH2 in tumor samples of STAD from the TCGA and GSE66229 datasets." (PMID 34222028, 2021). "Results illustrated that ITGA2, ITGA3, ITGA4, ITGA6, ITGA11, and ITGAV transcripts were increased in ESCC tumour tissues (n = 95) compared with normal tissues (n = 11)." (PMID 34709754, 2021). "We next verified the protein levels of the integrin α‐subunits suggested to be differentially represented between samples at the mRNA level, including ITGA2, ITGA3, ITGA4, ITGA6, ITGA11, and ITGAV using 10 paired (tumour and adjacent) ESCC patient tissues." (PMID 34709754, 2021). "We further examined the expression and localization of ITGA11 and COL11A1 in human CAFs and tumor tissues derived from NSCLC patients to validate ITGA11 and COL11A1 as specific cancer stroma biomarker." (PMID 33682233, 2021). "The results revealed that the expression levels of ITGA11, ITGB4 and ITGB8 were all significantly upregulated in tumor tissues compared with normal tissues." (PMID 31875161, 2019). "We also performed a data-mining analysis to investigate the differences in the expression levels of ITGA11, ITGB4 and ITGB8 between tumor and normal tissues in NSCLC using GEO datasets." (PMID 31875161, 2019). "Gene ontology analysis of these DEGs showed that in advanced stage tumours, pathways such as cell adhesion (VCAN), ECM receptor interaction (COL1A2, COL3A1, ITGA11, and TNN) and pathways in cancer (JUN, and MYC) getting deregulated." (PMID 31292488, 2019). "At a 5:1 tumor cell-N-MSC ratio, tumor cell presence appeared to attenuate ITGA11 upregulation by TGF-β in sample 21 N-MSCs (right column)." (PMID 29503225, 2018). "Our results confirm the tumor-suppressive role of SRD5A2 and the oncogenic role of ITGA11 in PCa." (PMID 35293897, 2022). "The ITGA11+/ COL11A1+ CAFs subtype, therefore, may serve as a key determinant for the progression of NSCLC and may be considered for novel anti‐tumor strategies through the blockade of cancer cell–stroma interactions." (PMID 33682233, 2021). "We, therefore, propose that targeting ITGA11 and COL11A1 expressing CAFs to block cancer–stroma interactions may serve as a novel, promising anti‐tumor strategy." (PMID 33682233, 2021). "In addition, we demonstrated that the ITGA11+ myCAF subgroup produced a cascade signalling under TGF‐β/TGFR activation and highly expresses ECM‐related genes such as COL11A1 and MMP11, assisting tumor cells in initiating the metastatic program." (PMID 41017455, 2025). "In contrast, none of the genes found in tumor fragments to be regulated by translation (LOX, WISP), abundance (FOXC1, COL5A2, ITGA11) or buffering (SNAI2) were modulated by mTORC1 in U87-MG cells." (PMID 31052505, 2019). "However, in our samples, the four genes were expressed in T-MSCs, and more modestly in N-MSCs but not (GREM1 and LOXL2) or weakly so (ITGA11 and ADAMTS12) in the tumor cells (data not shown)." (PMID 29503225, 2018).
cancer (38 papers, 2012 to 2025). A tumor composed of atypical neoplastic, often pleomorphic cells that invade other tissues. "Upregulation of ITGA11 expression increased migration of cancer-associated fibroblasts, while reduced expression of this gene in dermal fibroblasts impaired their migratory capacity." (PMID 41100455, 2025). "In a previous study, it has been reported that ITGA11 regulated JNK phosphorylation in cancer-associated fibroblasts." (PMID 38235326, 2024). "Of these dysregulated ITGs, ITGA11 was also upregulated and associated with poor prognosis in multiple cancer types, such as BRCA, GBM, LUAD, LUSC, STAD and THCA." (PMID 34222028, 2021). "While ITGA11 promotes myofibroblast differentiation and collagen reorganization, cancer–stromal ITGA11 expression has been found to be associated with cancer cell metastatic potential." (PMID 33682233, 2021). "Mechanically, over-expressed ITGA11 promoted the cancer-associated fibroblasts (CAF) migration via ERK1/2 signalling pathway in NSCLC." (PMID 34182990, 2021). "In addition, overexpressed ITGA11 accompanied by COL11A1 expression in cancer stroma was associated with a poor clinical outcome." (PMID 33682233, 2021). "Furthermore, function enrichment analysis revealed that ITGA11 was associated with KEGG pathways in cancer, as well as the epithelial-mesenchymal transition process, indicating the key role of ITGA11 overexpression in tumorigenesis and progression." (PMID 34222028, 2021). "Furthermore, overexpressed ITGA11 in cancer stroma was clinically associated with high recurrence following surgical resection, as well as with progression of pathological stage in NSCLC patients." (PMID 33682233, 2021). "In addition, ITGA11 was overexpressed by cancer-associated fibroblast (CAFs) in Pancreatic Ductal Adenocarcinoma (PDAC) stroma and may serve as an interesting stromal therapeutic target." (PMID 31875161, 2019). "Notable downregulated genes included Mki67, Ccn1, Muc1, Atf3, Ntrk2, Arid5b, Igf1r, Igf2bp2, Cd47, and Cd37 (oncogenic function) and integrin-related genes, Itga7, Itga11, Itgam and Notch1 (cancer stem cell markers)." (PMID 39946195, 2025). "Because both EZH2 and ITGA11 genes supporting CSCs were overexpressed in the resistant cells, a cancer stem cell TF activation profiling array was conducted to identify regulatory transcription factors (TFs) responsible for the genes." (PMID 38664825, 2024). "Consistently, the gene expression of collagen I receptors, linked to active tissue remodeling and cancer, including DDR2, ITGA2, ITGA10, ITGA11 and ITGB1 was higher in OS compared to RMS, whilst DDR1 expression was higher in RMS tumors." (PMID 35957513, 2022). "Blockade of ITGA11 gene expression reduces ERK activation in cancer cells; therefore, we examined the phosphorylation status of ERK1/2 in CAFs compared to control fibroblasts." (PMID 33682233, 2021). "We also analyzed the H‐score of ITGA11 in the cancer stroma and cancer epithelium at different pathological stages." (PMID 33682233, 2021). "Increased ITGA11 expression in cancer stroma was correlated with a poor clinical outcome in patients with NSCLC." (PMID 33682233, 2021). "Both ITGA11 and COL11A1 were highly expressed in cancer stroma compared to normal lung tissue and the expression level of ITGA11 correlated with that of COL11A1, suggesting interaction with the cancer stroma." (PMID 33682233, 2021). "We selected potential miR-148a cancer-related target genes, namely ITGA11, ITGB8, VAV2, ROCK1 and WASL, which are known to be involved in integrin pathway-promoting cell migration, motility, actin polymerization, and cytoskeleton remodeling." (PMID 25277193, 2014). "ITGA11 mRNA expression has been found to play a significant role in cancer prognosis." (PMID 41373732, 2025). "These may have contributed to further activation of the cancer stroma by the interaction of the infiltrating ITGA11+/ COL11A1+ CAFs with the cancer microenvironment." (PMID 33682233, 2021).
cancer (continued). "In addition, ITGA11‐deficient mice showed decreased α‐SMA expression co‐localized with ITGA11 in the cancer stroma." (PMID 33682233, 2021). "We hypothesized that ITGA11 and COL11A1 may regulate altered CAF phenotypes and could play a role in cancer progression and associated poor prognoses." (PMID 33682233, 2021). "Correlation between ITGA11 and COL11A1 expression levels in cancer‐associated fibroblasts." (PMID 33682233, 2021). "In addition, the H‐score of ITGA11 in the cancer stroma was significantly higher in the relapse group than that in the nonrelapsed group following surgery, however, not in the cancer epithelium." (PMID 33682233, 2021). "Moreover, function enrichment analysis also revealed that the pathways in cancer, epithelial-mesenchymal transition and inflammatory response signatures were enriched in ITGA11 overexpressed STADs from the two datasets." (PMID 34222028, 2021). "ITGA11 plays a significant role in cancer migration and invasion, leading to higher recurrence." (PMID 32719712, 2020). "Given that cancer cells can induce specific transcription of circRNAs by modulating the activation of numerous transcription factors, we evaluated potential transcription factors that interact with the circTAX1BP1 promoter and may be involved in the upregulation of circTAX1BP1 in ITGA11+ myCAF." (PMID 41017455, 2025). "However, conditioned mediums (CMs) from shITGA11 pancreatic satellite cells (PSCs) caused tumor cells to migrate and invade less than their counterpart, indicating the paracrine effects of this myCAFs marker, ITGA11, to cancer invasion by unknown secretion factors." (PMID 38892190, 2024). "Stromal ITGA11 expression affects the tumorigenicity and metastatic potential of NSCLC cells, as ITGA11 overexpression in CAFs increases their interaction with cancer cells." (PMID 33682233, 2021). "Intratumoral expression levels (H‐score) of ITGA11 and COL11A1 in cancer epithelium and cancer stroma were significantly higher than those in normal lung tissue." (PMID 33682233, 2021). "This leads to further CAFs with specific phenotype: ‘ITGA11+/ COL11A1+ CAF’, through the CAF–cancer cell interaction." (PMID 33682233, 2021). "TGF‐β1‐induced fibronectin also resulted in excessive deposition of COL11A1, accompanied by ITGA11 expression in the cancer stroma, resulting in a CAF‐specific phenotype: ITGA11+/ COL11A1+ CAFs." (PMID 33682233, 2021). "Numerous studies have suggested that ITGA11, ITGB4 and ITGB8 are involved in migration, epithelial-mesenchymal transition, invasion, and metastasis in different cancers." (PMID 31875161, 2019). "Meanwhile, other cell-cell adhesion-related molecules, such as laminins (LAMA4, LAMA5, LAMB1, LAMB2 and LAMC2) and integrins (ITGA5, ITGA5, ITGB5, ITGA11 and ITGBL1), are elevated in cancer tissues." (PMID 22905095, 2012). "Membrane molecules LRRC15, ITGA11, SPHK1 and FAP could be used as therapeutic targets for CSF-targeting cancer treatment." (PMID 36744260, 2023). "We demonstrated that CSFs could be potential targets for cancer treatment, and membrane molecules FAP, LRRC15, ITGA11 and SPHK1 could be used as CSFs specific targets." (PMID 36744260, 2023). "Furthermore, we found that some ITGs such as ITGA3, ITGA6 ITGA11, ITGB4, ITGB6, etc. were frequently upregulated in human cancers, whereas ITGs including ITGA1, ITGA7, ITGA8, ITGA9 and ITGB3, etc. were usually downregulated." (PMID 34222028, 2021). "Integrins, including TGA5, ITGA5, ITGB5, ITGA11, and ITGBL1 elevated in cancer tissues." (PMID 29843204, 2019). "The aberrant expression of ITGA11, ITGB4, and ITGB8 have been reported in many cancers." (PMID 31875161, 2019). "Additionally, ERK1/2 signaling induced ITGA11 and COL11A1 expression in cancer stroma." (PMID 33682233, 2021). "Thus, ITGA11 expression level in the cancer stroma involving CAFs serves as the crucial surrogate biomarker rather than that in the cancer epithelium itself." (PMID 33682233, 2021).
cancer (continued). "We found that LRRC15, ITGA11 and SPHK1 were also specifically expressed on CSFs, but not in other clusters of fibroblasts, indicating that they could also be attractive CSFs specific targets for cancer treatment." (PMID 36744260, 2023).
infection (3 papers, 2010 to 2018). The state of being infected such as from the introduction of a foreign agent such as serum, vaccine, antigenic substance or organism. "It is possible that ITGA11 may play a role in modulating cellular immune responses, by influencing the recruitment and adhesion of immune cells at sites of infection, or ectoparasite infestation." (PMID 20565915, 2010). "Furthermore, several cell adhesion molecules, including integrins, lectins, and cadhesion, were strongly upregulated by infection in CHB, such as conglutinin-like (COLEC8, 451.7 fold), integrin, α11 (ITGA11, 3.4 fold), and lectin, galactoside-binding, soluble, 15 (LGALS15, 340.1 fold)." (PMID 27197554, 2016).
ITGA11 also shares sentences with these, for which no sentence is quoted: glioblastoma (2 papers); head and neck cancer (2); atherosclerosis (1); basal cell carcinoma (1); cervical cancer (1); colorectal tumor (1); COVID-19 (1); dementia (1); diabetic nephropathy (1); dilated cardiomyopathy (1); head and neck squamous cell carcinoma (1); hereditary spastic paraplegia (1); human papillomavirus infection (1); lymph node metastasis (1); mucinous adenocarcinoma (1); muscular dystrophy (1); osteoarthritis (1); ovarian carcinoma (1); pancreatic adenocarcinoma (1); papillary thyroid carcinoma (1); spinal cord injury (1); staphylococcus aureus infection (1).